BCL6 (BCL6 transcription repressor)
Diseases named in the same sentence as BCL6 in open-access papers (continued):
Sharing a sentence is not in itself a finding about the gene and the disease.
cancer (continued). "Interestingly, using antibody depletion experiments, we found that only CD4+T cell deletion but not CD8+T cells deletion aborted T lymphocyte cytotoxicity against HCC after Bcl6 knockout in cancer cells." (PMID 38956432, 2024). "Second, from the single-cell RNA sequencing data, CyTOF data as well as the flow cytometry results, we can tell that in addition to T cells, other innate immune cells percentage was also upregulated upon Bcl6 knocking out including NK cells, which was reported to eliminate cancer cells in HCC34." (PMID 38956432, 2024). "Therefore, we conclude that CD4+T cells play an important role in HCC immune surveillance, and cancer cell-derived Bcl6 inhibited CD4+T cell function to assist HCC immune evasion." (PMID 38956432, 2024). "Given B cells’ role in cancer immunity, we believe that BCL6 could be used for cancer surveillance and treatment in next time." (PMID 39582536, 2024). "Moreover, the transcripts of the following notional cancer genes were significantly increased: Rbl1, Bcl2l11, Map3k2, Bcl6, Ppp1, Cdc42, and Ppp2." (PMID 38731901, 2024). "This study shows significant C–X bond cleavage in protein–ligand structures of the therapeutic cancer targets B-cell lymphoma 6 (BCL6) and heat shock protein 72 (HSP72) complexed with halogenated ligands, which is dependent on the type of halogen and chemical structure of the ligand." (PMID 39628887, 2024). "For instance, both Bcl6 and the MKL/SRF complex are linked to the development of cancer, and the interaction of these two pathways could lead to drug resistance." (PMID 37967194, 2023). "BCL6 inhibition impedes the growth of KRAS-mutant cancer cells in vitro." (PMID 36377663, 2022). "Considering the high prevalence of RAS point mutations in human tumors and the responsive role of BCL6 in KRAS oncogenic signaling, BCL6 inhibition may improve antitumor activity as a widely applicable approach in cancer therapy." (PMID 36377663, 2022). "All these data indicate that BCL6 blockage could restore the sensitivity of cancer cells to genotoxic agents." (PMID 35503721, 2022). "Importantly, addition of BCL6-targeted therapy to the genotoxic agent etoposide markedly restored the sensitivity of cancer cells to chemotherapy in vitro and in vivo." (PMID 35503721, 2022). "To test whether BCL6 induction creates an actionable vulnerability, we treated KRAS-mutant cancer cells with BCL6 chemical inhibitors." (PMID 36377663, 2022). "Furthermore, BCL6 knockdown dramatically reduced the clonogenic growth of various KRAS-mutant cancer cell lines." (PMID 36377663, 2022). "BCOR acts as a corepressor of BCL6, a potent oncogenic protein in cancers of the lymphoid lineage." (PMID 33468080, 2021). "As BCL6 has been well characterized as an oncogene, our results may have important implications in cancer treatment or prevention." (PMID 32412910, 2020). "This becomes particularly critical if the cells expressing BCL6 are cancer stem cells." (PMID 32320427, 2020). "If this is confirmed upon further analysis it might suggest BCL6 is enriched in cancer stem cells that inhabit the perivascular niche." (PMID 32320427, 2020). "Our RT-PCR analysis showed that BCL6 was expressed in carcinoma cell lines with silenced ZBTB28." (PMID 31754389, 2019). "Concerning follicular helper T cells (Tfh), an additional effector subset of T helper lymphocytes whose development is controlled by the B-cell lymphoma 6 transcription factor (Bcl-6), the presence of Tfh was high in various human cancers including malignancies in the lymphoid system." (PMID 27237631, 2016).
cancer (continued). "Since JNK signalling is central to many cooperative interactions examined by us and others, inhibiting the JNK pathway in addition to Bcl6 in Bcl6-driven cancers might also be a promising therapeutic approach to combat these cancers." (PMID 26187947, 2015). "Furthermore, in the Rohrbeck Lung (all-Lung, cancer only) dataset Bcl6 expression was positively correlated with MAP2K4, Yes1 and negatively correlated with Dlg2 and Lgl1." (PMID 26187947, 2015). "Also note that two genes, IL1A and BCL6, were identified differentially expressed in both the normal and the cancer cells." (PMID 24725556, 2014). "An inducible transgenic mouse model that is doubly transgenic for the tetracycline-responsive tet-o-bcl6 gene and the tissue-specific tetracycline-transactivating protein EμSR-tTA has been constructed to investigate the role of Bcl6 in this type of cancer in detail." (PMID 24860787, 2014). "Of those differentially expressed in our study, 14q32 miRNAs having confirmed targets include miR-127 (located within a CpG island and silenced in many cancers) targeting BCL-6, miR-154 targeting CCND2, miR-433 targeting HDAC6, miR-485-3p targeting NF-YB and miR-539 targeting HLCS." (PMID 23717541, 2013). "Importantly, most of these identified genes, such as FLT1, EBI3, LEP and BCL6, are highly involved in angiogenesis and immune modulation in malignant tumor progression." (PMID 22929622, 2012). "In various human cancer cell lines and mouse models, ETF insufficiency caused by decreased ETFDH expression limits flexibility of OXPHOS fuel utilisation but paradoxically increases bioenergetics and accelerates neoplastic growth via activation of the mTORC1/BCL-6/4E-BP1 axis." (PMID 42085321, 2026). "Notably, genes associated with these conversions, like BCL6 and BACH2, are downregulated more swiftly than others when subjected to JQ1, a super-enhancer-disrupting bromodomain and extra-terminal domain inhibitor utilized in cancer chemotherapy." (PMID 40631184, 2025). "Finally, BCL6 facilitates therapy resistance across a range of cancer types." (PMID 39456751, 2024). "Thus, we identified two biomarkers (CXCL1 and BCL6) for the diagnosis of colitis-related cancer." (PMID 39582536, 2024). "Based on these findings, we assume that increased BCL6 expression may be an adaptive surge in the cellular response to oncogene- or nononcogene-induced stress, highlighting the multifaceted role of BCL6 in cancer and the broad application of BCL6-based therapy." (PMID 36377663, 2022). "Thus, increased miR-127 expression in cancer cells may have an anticancer effect by inhibiting BCL6." (PMID 34234862, 2021). "Additionally, we examined further whether ZBTB28 expression antagonizes the cancer-promoting activity of BCL6 in carcinoma cells." (PMID 31754389, 2019). "These lymphoid structures were also positive for follicular markers CD21 and CD23 and contained Bcl6+CD4+ TFH cells, which are all characteristics of mature TLS in human cancers, distinct from immature lymphocyte aggregates." (PMID 40897896, 2025). "Genes like BCL6 and BACH2 tied to these conversions are downregulated faster by JQ1, a super-enhancer-disrupting anti-cancer agent." (PMID 40998810, 2025). "However, by comparing the effect of Bcl6 on HCC progression in immunocompetent mice and immune-deficient mice, it is reasonable to conclude that the effect of BCL6 on HCC progression through immune microenvironment is much more prominent than its effect on cancer cell growth." (PMID 38956432, 2024). "CCT373566 thus represents an excellent tool to probethe function of BCL6 in human cancer cells and xenografts models.We will publish the efficacy of CCT373566 in other BCL6-expressingmodels in due course." (PMID 35653645, 2022).
cancer (continued). "The increased expression of BCL6 further repressed the tumor suppressor PTEN and consequently enabled resistant cancer cell survival." (PMID 35503721, 2022). "For example, the checklist published by King and Lam (2019) would suggest DLBCL, NOS as an appropriate diagnosis for our patient, given that his cancer was a cyclin-D1-, CD10+, BCL6-, lymphoid, large B-cell lesion with a high labeling of Ki-67." (PMID 36158446, 2022). "Validated targets of miR-9-5p are BCL6, a nuclear protein with transcriptional repressor activity, and SIRT1, a class III histone deacetylase having multiple functions in cancer progression." (PMID 36293105, 2022). "Specifically, the TCGA datasets were integrated to evaluate the correlations of LATS2 expression with the four specific immune cell gene markers (PTPRC, BCL6, NRP1, and THBD) in 33 cancer types." (PMID 34699318, 2021). "Knockouts of some “cancer drivers” of DLBCL, including BCL2, BCL6, NFKBIA and CD70, showed only modest promotional effects on cell proliferation." (PMID 33911074, 2021). "Based on literature information, oncogenic states are defined as abnormal marker combinations, e.g., expression of BCL6 in combination with BCL2 and/or MYC is an aggressive cancer state." (PMID 34829885, 2021). "For example, YTHDF1 expression had a strong association with STAT1 in Th1 cells, STAT6 in Th2 cells, STAT3 in Th17 cells, STAT5B in Treg cells, BCL6 in Tfh cells, and IRF5 in M1 macrophages in most cancer types." (PMID 34026603, 2021). "The phenotypes of cancer cells are CD20+, CD79a+, bcl2+, CD10–, bcl 6+/–, FOX-P1, and MUM-1/IRF-4 positive." (PMID 32528871, 2020). "The phenotype of cancer cells shows variable expression of CD20 and presents CD19+, CD79a+, CD10-, BCL2+, PAX5+, BCL6-, and MUM-1/IRF-4+." (PMID 32528871, 2020). "Meanwhile, data from TCGA online database confirmed an inverse relationship between ZBTB28 and BCL6 expression in lung and ESCC carcinomas." (PMID 31754389, 2019). "In line with previous observations, genes involved in cancer development were represented on Bs of four studied species: red fox (KIT), Chinese raccoon dog (ENPP1, GNAS, HMGCR, KDR, RET), brocket deer (BCL6, RASA1, RET), and Korean field mouse (JAK3)." (PMID 30103445, 2018). "Twelve genes were frequently targeted in both cohorts independently, including BCL2, BCL6, BCL7A, CD74 and CIITA, all listed as oncogenes in the Cancer Gene Census and known to be involved in lymphomagenesis." (PMID 25903198, 2015). "All these genes have already been associated with hypermutated regions in BCLs (BCL2, BCL6, BCL7A, BIRC3, CIITA and ST6GAL1) or listed in the Cancer Gene Census (BCL2, BCL6, BCL7A, BIRC3, CIITA, IGLL5 – in the IGL@ locus – and LPP)." (PMID 25903198, 2015). "To date, only limited targets including miR-155, IRF5, Blimp1, CCNB1, BCL6, CDK6, Myc, and several others have been identified as IRF4 targets in cancers." (PMID 25207815, 2014). "Neither of the two ER- and AR-positive cancer samples exhibited elevated BCL6 levels in our analysis." (PMID 40729351, 2025).
cancer (continued). "Here in HCC, high expression Bcl6 was observed in HCC cancer cells but not in the microenvironment cells and correlated with poorer clinical outcome." (PMID 38956432, 2024). "It is also worth noting that no other types of tumors or cancers were found in Fbw7ΔEC mice, likely due to the fact that Bcl6 is exclusively expressed in germinal center B cells, but not in erythroid-myeloid progenitors and other hematopoietic cell types." (PMID 38485719, 2024). "We applied immunohistochemical staining to determine the mRNA expressions of CXCL1 and BCL6 in nontumor adjacent, UC and cancer tissues." (PMID 39582536, 2024). "The binding between B-cell lymphoma 6 protein (BCL6) and genome can recruit diverse chromatin-modifying co-repressor complexes to inhibit gene expression, in order to promote tumorigenesis and cancer progression, such as DNA damage sensing and proliferation checkpoints." (PMID 36522474, 2023). "Our patient's cancer did have an MYC rearrangement but not BCL2 or BCL6 rearrangements, and cells displayed both mature and immature markers, making HGBL, NOS a possible diagnosis." (PMID 36158446, 2022). "BCL6 expression was increased upon KRAS activation in lung tumor tissue in mice and was positively correlated with the expression of KRAS-GTP, the active form of KRAS, in various human cancer cell lines." (PMID 36377663, 2022). "Furthermore, LATS2 expression was positively correlated with the expression of PTPRC, BCL6, NRP1, and THBD in almost all cancers in the TCGA database." (PMID 34699318, 2021). "Regarding hsa-miR-299::CDKN2C (top 479) and hsa-miR-301::BCL6 (top 593) in the 44 multi-cancer-related pairs, they are not listed in the ground-truth data." (PMID 28105958, 2016). "BCL6 was highly expressed in differentiated cancers and was remarkably reduced or absent in undifferentiated cancers." (PMID 19337254, 2009). "There was a statistically significant difference in the histological type of BCL6-positive vs BCL6-negative cancers (P<0.05)." (PMID 19337254, 2009). "However, few studies have investigated the therapeutic efficacy of combining ICB with BCL6 inhibitors; it may be worth further exploration, particularly for treating NSCLC and AML cancer models." (PMID 41145211, 2026). "Understanding the consequences of Bcl6 cross-talk with RhoA/MKL/SRF in the brain and other organs during development and adulthood could be key to developing effective treatments for complex diseases such as developmental disorders and cancer." (PMID 37967194, 2023). "miR-10a′s negative impact on BCL6 suggests that it will have a role in cancer." (PMID 35906392, 2022). "However, the KEGG pathway “Transcriptional misregulation in cancer” were represented with four genes mapping to the pathway (Bcl6, Zbtb16, Aff1, and Dusp6), but not significant (adj." (PMID 34428250, 2021). "As expected, BCL6 promoted the growth of HONE1 carcinoma cells that lacked ZBTB28 expression." (PMID 31754389, 2019). "Therefore, understanding the fine tuning between apoptosis and lymphomagenesis as exemplified by the presented feedback loop between BCL6 and LITAF may offer hope for cancer diagnosis and therapy." (PMID 27764808, 2016). "These cancer cell lines also did not express endogenous BCL6 protein." (PMID 19337254, 2009).
cancer (continued). "We also applied immunohistochemistry to visualize the location of BCL6 in HCC and found that high expression of BCL6 was located in cancer cells but not in the stromal cells." (PMID 38956432, 2024). "The phenotypes of cancer cells are CD20+, CD79a+, CD5−, CD10+/−, bcl 6+, and MUM-1/IRF-4 negative." (PMID 32528871, 2020). "In addition, Aid is also reported to generate point mutations and/or double strand breaks at non-Ig locus, for example BCL6, MYC, PIM1 and PAX5, which are related to the cancer genesis." (PMID 24718089, 2014).